TRAF2 (TNF receptor associated factor 2)
Diseases named in the same sentence as TRAF2 in open-access papers (continued):
Sharing a sentence is not in itself a finding about the gene and the disease.
gastric cancer (continued). "TRAF2 could be considered as an independent prognostic factor in gastric cancer patients." (PMID 31130821, 2019). "It is possible that TRAF2 was a substrate of CHIP and CHIP regulated the TRAF2/NF-κB axis, which modulated diverse cellular behaviors in the AGS gastric cancer cells." (PMID 31130821, 2019). "CHIP regulated the TRAF2/NF-κB axis, which modulated diverse cellular behaviors of the AGS gastric cancer cells." (PMID 31130821, 2019). "Gastric cancer tissue microarray was analyzed to investigate the expression of both CHIP and TRAF2, and their clinical significance." (PMID 31130821, 2019). "The results suggest that miR‐141 targets Cbl‐b and c‐Cbl to prevent TRAF2‐mediated polyubiquitination and degradation of caspase‐8, and thus increases TRAIL sensitivity in gastric cancer cells." (PMID 28972304, 2017). "In this study, we demonstrated that DR5, Cbl‐b/c‐Cbl, and TRAF2 form a complex in TRAIL‐resistant gastric cancer cells and that Cbl‐b and c‐Cbl were the critical adaptors linking DR5 and TRAF2." (PMID 28972304, 2017). "Above all, TRAF2 was the responsible ubiquitin ligase for the K48 polyubiquitination of caspase‐8, and mediated TRAIL resistance in gastric cancer cells." (PMID 28972304, 2017). "Taken together, our results showed that DR5, Cbl‐b/c‐Cbl, and TRAF2 form a complex in TRAIL‐resistant gastric cancer cells and that Cbl‐b and c‐Cbl are the critical adaptors linking DR5 and TRAF2." (PMID 28972304, 2017). "Therefore, it was possible that TRAF2 was a substrate of CHIP and CHIP regulated the TRAF2/NF-κB axis, which modulated diverse cellular behaviors of the AGS gastric cancer cells." (PMID 31130821, 2019). "Therefore, it is possible that TRAF2 was a substrate of CHIP and CHIP regulated the TRAF2/NF-κB axis, which modulated diverse cellular behaviors of the AGS gastric cancer cells." (PMID 31130821, 2019). "We next performed immunoprecipitation and western blot analysis, but did not observe an interaction between DR5 and TRAF2 in gastric cancer cells without or with TRAIL treatment." (PMID 28972304, 2017). "To further identify the effect of DR5‐Cbl‐b/c‐Cbl‐TRAF2 complex on TRAIL sensitivity, we examined the expression of these proteins in TRAIL‐resistant (BGC823 and MGC803) and TRAIL‐sensitive (HGC27 and MKN45) gastric cancer cells." (PMID 28972304, 2017). "However, our data showed that the silencing of CUL3 or FLIP/L did not influence K48‐linked polyubiquitination of caspase‐8, and the silencing of CUL3 also did not change the interaction between TRAF2 and caspase‐8 in gastric cancer cells." (PMID 28972304, 2017).
hepatocellular carcinoma (12 papers, 2018 to 2025). A malignant tumor that arises from hepatocytes. "The results of our in vitro experimental studies confirmed that the loss of TRAF2 function inhibits the malignant behavior of HepG2 cells in hepatocellular carcinoma." (PMID 40144665, 2025). "In vivo results demonstrated that TRAF2 was closely associated with T lymphocytes in hepatocellular carcinoma." (PMID 40144665, 2025). "In liver cancer, low expression of TRAF2 was associated with an unfavorable prognosis, and loss of TRAF2 can induce caspase-8 hyperactivation and impaired NF-κB activation, promoting the tumorigenesis and progression of hepatocellular carcinoma." (PMID 37415241, 2023). "In addition, TRAF2 was found to be strongly associated with immune cell infiltration in tumor microenvironment and efficacy of immunotherapy, with particular association with T cells, which was experimentally validated in hepatocellular carcinoma." (PMID 40144665, 2025). "Overall, OS, DSS, and PFI were significantly lower in hepatocellular carcinoma patients with high TRAF2 expression (hazard ratio [HR] > 1.5, p < 0.001)." (PMID 40144665, 2025). "We knocked down TRAF2 in hepatocellular carcinoma HepG2 cells, and silencing TRAF2 resulted in a significant reduction in cell proliferation, intracellular lactate content, cell cycle, and migratory and invasive ability." (PMID 40144665, 2025). "TRAF2 represents a potential prognostic biomarker and therapeutic target for cancer immunotherapy, particularly in patients with hepatocellular carcinoma." (PMID 40144665, 2025). "Single-cell sequencing data and multiple immunofluorescence staining were used to observe the co-expression of TRAF2 on hepatocellular carcinoma cells and immune cells." (PMID 40144665, 2025). "A part of the study showed that activation of the mTORC1 pathway by TRAF2 promotes the proliferation and survival of hepatocellular carcinoma." (PMID 40144665, 2025). "Alterations in TRAF2 gene expression have also been found in diffuse large B-cell lymphoma and hepatocellular carcinoma." (PMID 39061149, 2024). "Baicalin treatment in hepatocellular carcinoma induces this repolarization, which is implemented by autophagy induction through activation of the RELB-p52 pathway and degradation of TRAF2 (TNF receptor associated factor 2)." (PMID 36497321, 2022). "For example TRAF2 expression was positively correlated with the therapeutic effect of Cladribine, and Cladribine was reported to have an anticancer effect on human hepatocellular carcinoma HepG2 cells." (PMID 35293027, 2022). "In human hepatocellular carcinoma (HCC), low expression of TRAF2 and its interacting partner RIP1 is associated with an unfavorable prognosis." (PMID 30294322, 2018). "Several studies have found that TRAF2 is upregulated in various types of cancers, including hepatocellular carcinoma, esophageal squamous cell carcinoma, lung squamous cell carcinoma, colorectal cancer, lymphoma, renal cell carcinoma, ovarian carcinoma, and gastric carcinoma." (PMID 40144665, 2025). "In addition, the invasiveness of hepatocellular carcinoma is affected by the TRAF2-regulated WNT/PI3K/NF-kb signaling pathway." (PMID 40144665, 2025). "Moreover, our study illustrated the role of TRAF2 on the malignant behavior of hepatocellular carcinoma cells and the correlation between TRAF2 and immune infiltration of T lymphocytes in the tumor microenvironment." (PMID 40144665, 2025). "TRAF2 (TNF receptor‐associated factor 2) expression was found to be significantly increased in cancer tissues and was associated with tumour metastasis in previous studies, but has rarely been reported in hepatocellular carcinoma." (PMID 35293027, 2022). "Therefore, co-targeting TRAF2 in conjunction with immune checkpoints or metabolic pathways may represent a novel strategy to enhance the efficacy of immunotherapy in hepatocellular carcinoma." (PMID 40144665, 2025).
hepatocellular carcinoma (continued). "TRAF2, particularly, has demonstrated elevated expression at both protein and mRNA levels in hepatocellular carcinoma (HCC) tissues." (PMID 38419066, 2024). "On the other hand, another study showed that combined genetic deletion of RIPK1 and TRAF2 in liver parenchymal cells contributed to the development of hepatocellular carcinoma, suggesting a suppressive role of TRAF2 in HCC tumorigenesis." (PMID 37081115, 2023). "For example, SPHK1, a regulator of sphingolipid metabolism, by binding TRAF2 (TNF receptor-associated factor 2) and Beclin-1, activates autophagy and thereby induces the degradation of E-cadherin, EMT, and the metastatic progression of hepatocellular carcinoma." (PMID 34944948, 2021). "In hepatocellular carcinoma (HCC), the ubiquitin-specific peptidase 24 (USP24) deubiquitinates and stabilizes TRAF2, which, in turn, promotes cell proliferation and metastasis." (PMID 40229245, 2025). "In conclusion, our study determined the prognostic and immunological roles of necroptosis‐related molecules such as TRAF2, PGAM5, ATG16L1, CADR9, PCYT1A, PARP2 and TLR2 in hepatocellular carcinoma." (PMID 35293027, 2022). "Genetic alterations of TRAF2 are detected in 1–2% of human hepatocellular carcinoma (HCC)." (PMID 31130821, 2019). "In line with human evidence, deletion of both TRAF2 and RIP1 in liver parenchymal cells (LPC) leads to spontaneous development of hepatocellular carcinoma, which results from extensive hepatocyte apoptosis due to hyperactivation of caspase-8 but impaired NF-κB activation induced by TNFα." (PMID 30294322, 2018).
colorectal cancer (11 papers, 2015 to 2025). A primary or metastatic malignant neoplasm that affects the colon or rectum. "Using various colorectal cancer mouse models, it is shown that the use of Traf2 and Nck-interacting protein kinase inhibitors (TNIKi) unexpectedly increases tumor infiltration by PD-1+ CD8+ T cells, thus contributing to tumor control." (PMID 35675910, 2022). "In the context of arginine metabolism in colorectal cancer (CRC) cells, the lncRNA LOC113230 functions as a scaffold for leucine-rich pentatricopeptide repeat-containing protein (LRPPRC) and TNF receptor-associated factor 2 (TRAF2), both of which are E3 ubiquitin ligases." (PMID 40804479, 2025). "Some evidence also suggested that CDCA3 interacting with TRAF2 could activate NF-κB pathway in colorectal cancer." (PMID 34384030, 2021). "In a TNF-α-stimulated tumour cell in the inflammatory colorectal cancer microenvironment, upon binding of TNF-α to its receptor TNFR1, adaptor proteins TRADD and TRAF2 are recruited with cIAP-1 and/or cIAP-2 and RIP kinase." (PMID 38600086, 2024). "TRAF2- and NCK-interacting kinase (TNIK) has emerged as a promising therapeutic target for colorectal cancer because of its essential role in regulating the Wnt/β-catenin signaling pathway." (PMID 36361804, 2022). "TRAF2- and NCK-interacting kinase (TNIK) represents one of the crucial targets for Wnt-activated colorectal cancer." (PMID 27650168, 2016). "We have previously identified TRAF2- and NCK-interacting protein kinase (TNIK) as an essential factor for the transactivation of Wnt signal target genes and shown that its inhibition leads to eradication of colorectal cancer stem cells." (PMID 33400690, 2021).
colitis (10 papers, 2015 to 2024). Inflammation of the colon. "In another study, TRAF2-deficient mice develop severe spontaneous colitis and exhibit altered colonic microbiota composition, indicating the anti-inflammatory role of TRAF2 in controlling colonic microbiota." (PMID 32848509, 2020). "A recent report demonstrated that TRAF-2 deficient mice spontaneously developed severe colitis due to enhanced TNFα-induced apoptosis of colonic epithelial cells." (PMID 27997590, 2016). "EZH2 reduction directly stimulates TRAF2/5 expression to enhance TNFα-induced NF-κB signaling, and promote inflammation and apoptosis in colitis." (PMID 39588368, 2024). "Additional studies found that myeloid cell-specific knockout of TRAF2 or TRAF3 aggravated colitis by promoting expression of pro-inflammatory cytokines stimulated by TLRs in macrophages." (PMID 34956195, 2021). "DSS-induced colitis models of TRAF2- and TRAF3-deficient mice reveal similar functions of TRAF2 and TRAF3 as negative regulators of experimental colitis by decreasing proinflammatory cytokines and reducing the infiltration of immune cells in the colon." (PMID 32848509, 2020). "The protective role of TRAF2 in colon inflammation has also been revealed using TRAF2 germline knockout mice, which spontaneously develop colitis." (PMID 30140268, 2018). "Consistent with a potential role of TRAF2 in colon tumorigenesis, germline TRAF2−/− mice spontaneously develop severe colitis, which results from TNFα-TNFR1-mediated apoptosis of TRAF2−/− colonic epithelial cells and altered colonic microbiota." (PMID 30294322, 2018). "Like TRAF3, TRAF2 negatively regulate induction of proinflammatory cytokines by the TLR ligands LPS and polyIC as well as by the cytokine IL-1β, and the myeloid cell-conditional TRAF2 knockout (TRAF2-MKO) mice are hypersensitive to colitis induction in the DSS model." (PMID 30140268, 2018). "Interestingly, myeloid cell-specific ablation of TRAF2 markedly exacerbates DSS-induced colitis in mice due to enhanced TLR-induced proinflammatory cytokine expression in macrophages." (PMID 30294322, 2018). "Recent studies suggest that TRAF2 could have a crucial role in adult tissue homeostasis; three-week-old Traf2-/-mice on the BALB/c background developed spontaneous colitis, and this phenotype was due to the death of the colonic epithelium." (PMID 26701909, 2015). "IL-10-secreting neutrophils might induce immunosuppression under certain conditions and aggravate colitis by enhancing colonic bacterial invasion, suggesting a potentially important role for TRAF2-mediated TNF-α signaling in regulating IL-10-mediated colonic homeostasis." (PMID 34956195, 2021). "Confocal immunostaining showed that the colocalization between LRRC19 and TRAF6 in DVF-treated colitis mice was highly visible, but colocalization of LRRC19 and TRAF2 was rarely observed." (PMID 38172943, 2024). "Studies have reported that TRAF2 plays a negative regulatory role in the expression of TLR-stimulated proinflammatory cytokines and inhibits the occurrence of colitis by reducing the expression of LPS-, poly(I:C)- and IL-1β-induced proinflammatory cytokines." (PMID 38037100, 2023). "Preliminary evidence linking TRAFs with intestinal inflammation was suggested by a study reporting that Traf2-/- mice, with BALB/C background, spontaneously developed severe colitis and died within 3 weeks after birth." (PMID 34956195, 2021). "Another difficulty with the Alvarez interpretation of their data is that Sphk1-/- mice are viable and relatively normal, while Traf2 knock-outs on a C57BL/6 background die before or shortly after birth and on a BALB/c background develop severe colitis and die within three weeks after birth." (PMID 26701909, 2015). "TRAF2 plays a cytoprotective role, enhance the survival of colonic epithelial cells and reduces inflammation in DSS-induced and spontaneous colitis, suggesting it is involved in the negative feedback process that restricts inflammation." (PMID 30931953, 2019).
colitis (continued). "Moreover, tumor suppressor HACE1 deficient mice were also highly sensitive to DSS-induced experimental colitis, likely because lack of HACE1 in IECs led to reduction of TRAF2 ubiquitin and overactivation of TNF-α-induced necrosis, and subsequent inflammation." (PMID 34956195, 2021).
glioblastoma (10 papers, 2016 to 2026). The most malignant astrocytic tumor (WHO grade IV). "Recent reports show that TRAF2 is of prognostic significance in glioblastoma and its inhibition suppresses proliferation of glioblastoma cells." (PMID 34117217, 2021). "Therefore, the MSI1/miR-671-5p/STAT3 axis enhances radioresistance, and the MSI1/miR-671-5p/TRAF2 axis activates glioblastoma stem cell-like properties and EMT-like abilities." (PMID 35052701, 2021). "To examine whether TRAF2-promoted proliferation of glioblastoma cells is mediated through DYRK1A, we first performed shRNA-mediated knockdown of DYRK1A using lentiviruses." (PMID 34117217, 2021). "However, another complex known as the preligand assembly complex (PLAC), containing TNF‐α‐induced protein 3 (TNFAIP3), receptor‐interacting protein (RIP), DR5, and TRAF2, has been found in glioblastoma." (PMID 28972304, 2017). "Previous work has shown that TRAF2 binds to DR5 and is localized to the PLAC in glioblastoma." (PMID 28972304, 2017). "Detailed examination indicated that the highest expressions of TRAF1, TRAF2, TRAF3, TRAF5, and TRAF7 were in Cholangiocarcinoma (CHOL), while TRAF4 was most expressed in Uterine Corpus Endometrial Carcinoma (UCEC) and TRAF6 in Glioblastoma multiforme (GBM)." (PMID 38825674, 2024).
pancreatic cancer (10 papers, 2008 to 2025). "Rapid growth is one hallmark of pancreatic cancer and our data indicates that the TRAF2/NIK/NF-κB2 pathway may be a valuable target for therapy of this cancer." (PMID 23301098, 2013). "In line with this statement, the overexpression of TRAF2 in pancreatic cancer cells was shown to protect these cells from CD95-mediated apoptosis, while the downregulation of TRAF2 enhanced extrinsic apoptosis." (PMID 39513921, 2024). "Silencing CPNE1 with siRNA reduced both CPNE1 and TRAF2 levels, decreasing pancreatic cancer cell proliferation." (PMID 39061149, 2024). "In pancreatic cancer cells, TRIM31 has been shown to upregulate nuclear P65 levels and sustain NF-κB activation by promoting K63-linked polyubiquitination of tumor necrosis factor receptor-associated factor 2 (TRAF2)." (PMID 40819060, 2025). "In addition, TRAF2 overexpression increases the invasive properties of pancreatic cancer cells by inducing the expression of proteolytic enzymes, like matrix metalloproteinases 2 and 9 or the urokinase type plasminogen activator (uPA)." (PMID 18652674, 2008). "The findings from this assessment indicated that TRAF2, TRAF3, TRAF5, and TRAF7 are effective in predicting the outcomes of pancreatic cancer." (PMID 38825674, 2024). "To bolster our mechanistic in vitro analysis, we analyzed 55 human samples of PDAC (grades 1–3) and found that approximately 69% showed decreased expression of TRAF2 and increased levels of NIK and pT559-NIK similar as we had observed it in pancreatic cancer cell lines." (PMID 23301098, 2013). "Notably, TRAF2 and TRAF7 demonstrate a significant positive correlation with the chemotherapeutic agents fluorouracil and gemcitabine, which are commonly used in the treatment of pancreatic cancer." (PMID 38825674, 2024). "Furthermore, ectopic expression of TRAF2 in the FASL-sensitive pancreatic cancer cell line Colo357 confers resistance towards FAS-mediated apoptosis, arguing for a pivotal role of TRAF2 in mediating FAS resistance of pancreatic cancer cells." (PMID 18652674, 2008).
viral infection (10 papers, 2013 to 2025). "The aggregation of VISA and the interaction of VISA and TRAF2 are enhanced in BAG6-deficient cell lines after viral infection, resulting in the enhanced transcription level of downstream antiviral genes." (PMID 36045679, 2022). "BST2 has also been reported to have a pro-inflammatory function through the Syk/TRAF2/TRAF6/TAK1/NF-κB pathway under conditions of viral infection." (PMID 35316682, 2022). "However, it is unclear whether and how the TRAF3-MFF, TRAF3-TRAF2, and TRAF2-cIAP1/2 interactions are affected by viral infection, ER stress, and mitochondrial membrane permeabilization in B cells." (PMID 36776285, 2023). "Following viral infection, both TRAF3 and TRAF2 are recruited to the mitochondrial antiviral signaling complexes by MAVS, while in response to ER stress, TRAF2 is translocated to ER via interacting with the ER stress sensor IRE1α." (PMID 36776285, 2023). "Since BIRC2/BIRC3 and TRAF2/3 could form a cytoplasmic complex, where BIRC2/BIRC3 mediated ubiquitination and degradation of TRAF3, the roles of BIRC2/BIRC3 in viral infection were extensively investigated." (PMID 34887869, 2021). "Our model that MAVS signals through multiple TRAF proteins is further supported by mutagenesis experiments which showed that mutations of both TRAF2/5 and TRAF6 binding sites of MAVS, but not each alone, abolished IRF3 and IKK activation by virus infection." (PMID 23951545, 2013). "However, the relationship between RIP-1 and the TRIF/TRAF1, TRAF2, and TRAF3 pathways to produce cytokines after viral infection is unknown." (PMID 25754842, 2015). "Furthermore, mutations of the binding sites for TRAF2, TRAF5, and TRAF6 on MAVS abolished the ability of MAVS to activate downstream signaling after virus infection, without affecting its ability to form prion-like polymers." (PMID 23951545, 2013). "In this study, we observed the TLR3/TRIF/RIP-1 pathway also involved in TRAF1, TRAF2 and TRAF3 activation, but not TRAF6 after stimulation by dsRNA or viral infection in the corneal epithelium." (PMID 25754842, 2015).